ROR1 (ROR family WNT receptor 1)
Diseases named in the same sentence as ROR1 in open-access papers (continued):
Sharing a sentence is not in itself a finding about the gene and the disease.
bipolar disorder (1 paper, 2011). A disorder of the brain that causes unusual shifts in mood, energy, activity levels and the ability to carry out day-to-day tasks. "The most significant SNPs resided in ROR1 and PLCB1, genes known to be involved in bipolar disorder and schizophrenia, respectively." (PMID 21494683, 2011).
breast adenocarcinoma (1 paper, 2012). "Evaluation of fresh-frozen tumor biopsy specimens (N = 4) with 4A5 revealed that breast adenocarcinomas expressed ROR1, in contrast to normal breast tissues (N = 2) which lacks expression of ROR1." (PMID 22403610, 2012). "Moreover, 10 out of 14 (72%) patients with poorly differentiated ductal breast adenocarcinoma (grade 3) had cancer tissue that expressed high levels of ROR1 protein." (PMID 22403610, 2012).
Burkitt lymphoma (1 paper, 2012). A rare form of malignant mature B-cell non-Hodgkin lymphoma. "A firm 120-kDa band, which we previously correlated with cell surface ROR1 in primary CLL cells, B-ALL cell lines, and primary B-ALL blasts (data not shown), was only detected in the positive control (Burkitt lymphoma cell line CA-46), but not in normal pediatric tissues." (PMID 23285131, 2012).
carcinosarcoma (1 paper, 2023). A malignant tumor composed of a mixture of carcinomatous and sarcomatous elements. "The SNU-539 cell line, a carcinosarcoma cell line derived from a uterine malignant mixed Müllerian tumor, exhibits a high expression of ROR1." (PMID 37241228, 2023). "The HEC-1 cell line, a model of Type II endometrial adenocarcinoma, and the SNU-539 cell line, a model of carcinosarcoma, exhibited higher expression of ROR1 protein and mRNA." (PMID 37241228, 2023).
cholangiocarcinoma (1 paper, 2024). A carcinoma that arises from the intrahepatic biliary tree (intrahepatic cholangiocarcinoma) or from the junction, or adjacent to the junction, of the right and left hepatic ducts (hilar cholangiocarcinoma). "For example, only 13.5% of cholangiocarcinoma human tumors tested expressed ROR1, while 74% of cholangiocarcinoma-derived xenografts in our PDX TMAs expressed ROR1." (PMID 38791952, 2024).
chronic pancreatitis (1 paper, 2024). A chronic inflammatory process causing damage and fibrosis of the pancreatic parenchyma. "In Western blot analysis ROR1 is expressed in non-cancerous pancreatic tissue (NC) as well as chronic pancreatitis (CP) and PDAC." (PMID 38846943, 2024). "Exosomes were isolated from PF and plasma samples of non-cancerous (NC) (n = 15), chronic pancreatitis (CP) (n = 4), localized PDAC (PER-) (n = 18) and peritoneal disseminated PDAC (PER+) (n = 9) patients and the surface protein ROR1 was detected via FACS analysis." (PMID 38846943, 2024).
colitis (1 paper, 2025). Inflammation of the colon. "Surprisingly, Tgfb1, Il17ra, Il23a, Il6ra, Ror1, Tnf, Tgfbr2, Ccr2, and Il17c were downregulated by cigarette smoke exposure in TNBS-induced colitis Gpr15−/− mice compared with similarly treated Gpr15+/+ mice." (PMID 40957881, 2025).
colorectal adenocarcinoma (1 paper, 2025). The most common type of colorectal carcinoma. "The model comprises human endothelial cells and macrophages cocultured with colorectal adenocarcinoma CaCo2 cells expressing the receptor tyrosine kinase‐like orphan receptor 1 (ROR1) protein." (PMID 40249196, 2025).
COVID-19 (1 paper, 2023). A disease caused by infection with severe acute respiratory syndrome coronavirus 2. "Of interest, among the significant plasma cytokines detected in COVID-19 patients, IL-8 showed a positive correlation with CD19, CD69 and ROR1 whereas IL-6 positively correlates with MFI CD24." (PMID 37207201, 2023).
cyst (1 paper, 2022). A sac-like closed membranous structure that may be empty or contain fluid or amorphous material. "It is tempting to speculate that upregulation of GPRC5A and ROR1 in cyst-lining cells might drive proliferation in the hypoxic milieu in ADPKD kidneys." (PMID 36310237, 2022). "Interestingly, we observed ROR1 protein expression in GPRC5A + cyst cells." (PMID 36310237, 2022). "Collectively, these findings suggest a potential role of ROR1 and GPRC5A in defining a unique gene signature of cyst-lining cells in ADPKD." (PMID 36310237, 2022).
dilated cardiomyopathy (1 paper, 2019). Cardiomyopathy which is characterized by dilation and contractile dysfunction of the left and right ventricles. "We identified genes that have previously been implicated in heart development and structural heart malformations (e.g. MBNL1, ROR1), and known disease-related genes (e.g. NEXN, dilated cardiomyopathy; NDUFS1, mitochondrial complex I deficiency)." (PMID 31314787, 2019).
endometrial adenocarcinoma (1 paper, 2023). "HEC-1 cells were engineered to overexpress ROR1 as a model of Type II endometrial adenocarcinoma." (PMID 37241228, 2023).
endometriosis (1 paper, 2025). The growth of functional endometrial tissue in anatomic sites outside the uterine body. "Rimegepant emerged in the drug repurposing pipeline due to potential interactions with ROR1, which appears stably expressed across the cycle in endometriosis lesions, while systemic CGRP levels fluctuate." (PMID 41415567, 2025). "In endometriosis, evidence suggests ROR1 is upregulated in stromal cells of ovarian endometriomas through epigenetic mechanisms, and Wnt5a contributes to stromal signaling and the immune microenvironment." (PMID 41415567, 2025). "Collectively, these observations highlight ROR1 as a biologically plausible target for therapeutic intervention in endometriosis, although its potential has yet to be experimentally validated." (PMID 41415567, 2025). "ROR1 expression was assessed in transcriptomic datasets including 408 endometriosis samples and 53 controls and validated at the protein level in an independent cohort of tissue microarrays comprising 179 tissues." (PMID 41415567, 2025). "This study aimed to validate ROR1 as a therapeutic target in endometriosis and to employ computational chemistry approaches to identify existing compounds with potential affinity for this receptor." (PMID 41415567, 2025). "ROR1 was transcriptionally upregulated in endometriosis and overexpressed at the protein level across lesions." (PMID 41415567, 2025). "This variability may relate to occult endometriosis in macroscopically normal peritoneum, or to ROR1’s involvement in biological pathways relevant to lesion pathophysiology, including inflammation, fibrosis, and neural remodeling." (PMID 41415567, 2025). "High ROR1 was significantly associated with lack of hormonal treatment and increased Ki67, but not with progesterone receptor status, surgical history, disease stage, Endometriosis Fertility Index, infertility, pain scores, family history, or co-diagnoses." (PMID 41415567, 2025). "Both deep infiltrating endometriosis (DIE) lesions and DIE with concurrent ovarian endometrioma (DIE + OMA) exhibited higher ROR1 levels than adjacent peritoneal tissue." (PMID 41415567, 2025).
epilepsy (1 paper, 2024). A brain disorder characterized by episodes of abnormally increased neuronal discharge resulting in transient episodes of sensory or motor neurological dysfunction, or psychic dysfunction. "Whether ROR1 reduction is involved in the development of epilepsy through inhibitory synaptic remodeling needs to be demonstrated in further experiments." (PMID 38585359, 2024). "Surprisingly, we also identified many differential proteins such as UGGT2, SEMG1, PDIA4, ROR1, NIF3L1, and ITIH4, that have not previously been directly reported with epilepsy." (PMID 38585359, 2024).
esophageal squamous cell carcinoma (1 paper, 2022). Esophageal squamous cell carcinoma (ESCC) is a type of esophageal carcinoma (EC) that can affect any part of the esophagus, but is usually located in the upper or middle third. "ROR1 strongly associates with ROR2, making up the receptor for Wnt5a signaling and activates RhoA through Daam1 in esophageal squamous cell carcinoma (ESCC) and glioblastoma." (PMID 35625853, 2022).
gastrointestinal stromal tumor (1 paper, 2024). "Among the 12 gastrointestinal stromal tumor (GIST) cases, we found that 33.3% showed ROR1 expression, with an average total ROR1 positivity in tumor areas of 14% (range 0–100%) and an average H-score of 38 (range 0–160)." (PMID 38791952, 2024).
insomnia (1 paper, 2011). A sleep disorder characterized by difficulty in falling asleep and/or remaining asleep. "Hence, dysregulation of ROR1, PLCB1, or PLCB4 by PAX6 and CTCF may be one mechanism that links neural and pancreatic dysfunction not only in insomnia but also in the relevant psychiatric disorders that are accompanied with circadian rhythm disruption and metabolic syndrome." (PMID 21494683, 2011).
invasive breast carcinoma (1 paper, 2025). A carcinoma that infiltrates the breast parenchyma. "Our findings revealed a statistically significant positive correlation between BRD4 and ROR1, particularly in prostate adenocarcinoma and invasive breast carcinoma." (PMID 39816690, 2025).
ischemia (1 paper, 2018). A hypoperfusion of the BLOOD through an organ or tissue caused by a PATHOLOGIC CONSTRICTION or obstruction of its BLOOD VESSELS, or an absence of BLOOD CIRCULATION. "ROR1 was identified as one of the RTKs that was both present in the ischemic heart in an active form and regulated in expression in a manner that associated with clinical and experimental ischemia." (PMID 30342492, 2018).
ischemic cardiomyopathy (1 paper, 2018). Ischemic cardiomyopathy is a cardiomyopathy in which a weakness in the muscle of the heart due to inadequate oxygen delivery to the myocardium with coronary artery disease being the most common cause. "ROR1 was the most significantly upregulated RTK in human ischemic cardiomyopathy." (PMID 30342492, 2018). "Moreover, ROR1 mRNA expression was upregulated in the ischemic cardiomyopathy samples." (PMID 30342492, 2018). "The most significantly up- and downregulated RTKs were ROR1 and EPHA2, respectively, when ischemic cardiomyopathy was compared to normal heart." (PMID 30342492, 2018).
liposarcoma (1 paper, 2024). A usually painless malignant tumor that arises from adipose tissue. "ROR1 membranous or cytoplasmic expression was identified in liposarcoma tumoral cells with an average positivity of 57.2% of tumor cells and an average H-score of 66.2." (PMID 38791952, 2024). "Intratumoral heterogeneity of expression was present in most tumor histologic types; however, liposarcoma cases exhibited consistently homogeneous ROR1 expression." (PMID 38791952, 2024).
low grade glioma (1 paper, 2019). A grade I or grade II glioma arising from the central nervous system. "Additionally, we performed Cox proportional hazard regression analysis for ROR1 mRNA in all 29 cancer types and found ROR1 has the worst prognosis in kidney papillary cell (KIRP) and low-grade glioma (LGG) with hazards ratios of 4.49 and 3.95, respectively." (PMID 31137681, 2019).
malignant mesothelioma (1 paper, 2024). A malignant neoplasm of the pleura or peritoneum, arising from mesothelial cells. "In conclusion, our study is the first to address the immunohistochemical ROR1 expression across several tumor types in a large sample cohort and to identify ROR1 prevalence in malignant mesothelioma." (PMID 38791952, 2024). "In our study, malignant mesothelioma showed the highest prevalence of ROR1 expression." (PMID 38791952, 2024).
malignant pleural mesothelioma (1 paper, 2024). A malignant neoplasm that arises from mesothelial cells in the pleura and shows a diffuse growth pattern. "Additionally, they examined the expression of ROR1 and ROR2 in human malignant pleural mesothelioma cell lines, finding higher ROR1 expression in H2452 cells than in other human lung mesothelioma cells." (PMID 38791952, 2024).
metastatic disease (1 paper, 2022). "In addition, compared to localized disease, 9 RTKs including receptor tyrosine kinase-like orphan receptor 1 (ROR1) have higher expression levels in metastatic disease, suggesting ROR1 contributes to metastasis." (PMID 36230825, 2022).
Moyamoya disease (1 paper, 2013). Moyamoya disease (MMD) is a rare intracranial arteriopathy involving progressive stenosis of the cerebral vasculature located at the base of the brain causing transient ischemic attacks or strokes. "Using the novel functional interpolating single-nucleotide polymorphisms bioinformatics approach, we identified 6 Moyamoya Disease-associated autoantibodies against APP, GPS1, STRA13, CTNNB1, ROR1 and EDIL3." (PMID 23518061, 2013).
neuroendocrine tumors (1 paper, 2023). "ROR1 expression in tumor cells was more frequent in non-squamous (87%) than in squamous (57%) carcinomas patients, while 21% of neuroendocrine tumors expressed ROR1 (p = 0.0001)." (PMID 37111634, 2023). "In non-squamous and squamous carcinomas, 86% and 56%, respectively, expressed ROR1, while in neuroendocrine tumors only about 20% exhibited ROR1." (PMID 37111634, 2023).
oral cancer (1 paper, 2025). "In HNSCC, siRNA-mediated ROR1 knockdown inhibited oral cancer cell proliferation." (PMID 40723210, 2025).
pancreatitis (1 paper, 2024). Inflammation of the pancreas. "Additionally, exo-ROR1 was expressed in qPCR in tissue of Non Cancer (n = 24), pancreatitis (n = 5), and PDAC patients (n = 26)." (PMID 38846943, 2024). "In the pancreatitis sample the islet cells are ROR1 positive, but the fibrotic tissue is negative." (PMID 38846943, 2024).
pneumonia (1 paper, 2025). An acute, acute and chronic, or chronic inflammation focally or diffusely affecting the lung parenchyma, caused by an infection in one or both of the lungs (by bacteria, viruses, fungi, or mycoplasma.). "Moreover, a clinical trial of receptor tyrosine kinase-like orphan receptor 1 (ROR1) CAR-T cells overexpressing c-Jun revealed a potential risk of treatment-related pneumonia in cancer patients with lung metastases." (PMID 40093905, 2025).
prostate tumors (1 paper, 2020). "Appropriate localization and persistence of T cells is a prerequisite for activity against solid tumors, so we next assessed the frequency of infiltrating ROR1 CAR-T cells into prostate tumors over time." (PMID 33247092, 2020). "We found that, in comparison to untreated LNCaP C42 prostate tumors, which express the ROR1 tumor antigen at various levels, CAR-targeted tumors in both treatment groups (adoptively transferred T cells or nanoparticle-programmed T cells) eventually developed ROR1 low/negative immune-escape variants." (PMID 33247092, 2020).
renal carcinoma (1 paper, 2014). A carcinoma arising from the epithelium of the renal parenchyma or the renal pelvis. "While these findings suggest that ROR1 expression is a hallmark of renal cancer, it is important to note that the protein levels of ROR1 are not measured in this study." (PMID 24752542, 2014). "Furthermore, PBMCs from renal cancer patients showed significantly higher ROR1 expression, compared to healthy controls." (PMID 24752542, 2014). "Although protein levels of ROR1 are low or not detectable within the kidney of healthy individuals, ROR1 mRNA can be detected in 81.3% of tissue samples and 94% of PBMCs samples from renal cancer patients as determined by RT-PCR." (PMID 24752542, 2014).
soft tissue sarcoma (1 paper, 2025). A malignant neoplasm arising from muscle tissue, adipose tissue, blood vessels, fibrous tissue, or other supportive tissues excluding the bones. "We describe the development, characterization, and preclinical validation of 22.0405.aF, a potential first-in-class afucosylated anti-ROR1 antibody, which recently completed Phase 0 clinical investigation (NCT06273852) in patients with head and neck carcinomas and soft tissue sarcomas." (PMID 41479906, 2025).
teratoma (1 paper, 2018). A non-seminomatous germ cell tumor characterized by the presence of various tissues which correspond to the different germinal layers (endoderm, mesoderm, and ectoderm). "Consistent with this, transplantation of ROR1+ cells into immunocompromised mice showed no teratoma formation unless hPSCs were deliberately transplanted with the ROR1+ cells." (PMID 29217756, 2018).